CHEK1 (checkpoint kinase 1)
Diseases named in the same sentence as CHEK1 in open-access papers (continued):
Sharing a sentence is not in itself a finding about the gene and the disease.
breast carcinoma (continued). "Nonetheless, the prognostic significance of CHEK1 in breast cancer (BrC) remains unclear." (PMID 40344565, 2025). "Furthermore, we also evaluated whether there is any positive correlation between RAD51 and CHEK1 expressions in breast cancer." (PMID 31492187, 2019). "We examined the expression levels and clinical relevance of CHEK1, CDC25A, CCNE1, hsa‐miR‐195‐5p, and hsa‐miR‐497‐5p in a comprehensive cohort of 217 breast carcinoma patients." (PMID 40548926, 2025). "Rabusertib, a selective checkpoint kinase 1/2 (CHEK1/2) inhibitor, is typically used to treat ovarian, non-small cell lung, and breast cancers." (PMID 41249113, 2025). "Research has shown that CHEK1 maintains genomic stability via the ATR-CHK1 signaling pathway, a mechanism conserved across all breast cancer subtypes." (PMID 40344565, 2025). "We identified several DEGs involved in the cell cycle, including CDK1, CHEK1, CDC25C, BUB1, CDC20, and TTK, which not only are related to breast cancer patient survival but also have existing targeted drugs." (PMID 38166892, 2024). "The interplay between EZH2 and other cell cycle targets (e.g., AURKA, CHEK1, CDKN1A) has also been reported in other contexts such as breast cancer, melanoma, non-Hodgkin’s lymphoma, T-cell acute lymphoblastic leukemia." (PMID 38405800, 2024). "The publicly available bc-GenExMiner V4.8 web–based tool was employed to investigate the specific expression patterns of CHEK1 and PLK1 in TNBC compared to other breast cancer subtypes." (PMID 39473450, 2024). "Currently, a variety of cell cycle checkpoint kinase inhibitors are also under research and their anti-tumor effects in combination with PARP inhibitors are evaluated, including inhibition of CHEK1/2, ATM, ATR, and WEE1 in breast cancer." (PMID 39334297, 2024). "FBXO6 controls the degradation of checkpoint kinase 1 (Chk1) and confers the sensitivity to certain anticancer drugs, including camptothecin, in tumor cells, such as non-small cell lung cancer, GBM, and breast cancer." (PMID 36998461, 2023). "A study through the breast cancer dataset and Gene Ontology (GO) database found that checkpoint kinase 1 (chk1) gene is significantly overexpressed in TNBC patients, and chk1 as a key target is involved in the DNA repair pathway to treat TNBC." (PMID 35414025, 2022). "Through proteome atlas, only the expression of CHK1, the protein of the CHEK1 gene, was uniquely enhanced in basal-like breast cancer patients compared with other subtype patients." (PMID 36547059, 2022). "In conclusion, the proofs in this study suggest that reduced miR-511-5p was a biomarker event for breast cancer, and CCNE1 and CHEK1 served as potential targets of miR-511-5p to involve the progression of breast cancer." (PMID 35186236, 2022). "After further validation through survival analysis and expression evaluation, CHEK1 and UBE2C were finally identified as hub genes related to the progression of BRCA, especially the luminal A breast cancer subtype." (PMID 35903365, 2022). "ZEB1 physically interacts with ATM in SUM159-P2 human breast cancer cells, such that ATM depletion significantly downregulates ZEB1 and checkpoint kinase 1 (CHK1) protein levels." (PMID 35454770, 2022). "MCM10 OE was able to increase RPA2 compared to controls in breast cancer patient biopsy and in MCF10A OE cells, which further induced high expression of downstream proteins ATR and CHEK1, supporting the possibility of increased ssDNA in MCM10 OE cells." (PMID 35813483, 2022). "Overexpression of CHEK1 activates the cell cycle and MAPK signaling pathways which were reported to be related to breast cancer onset and development." (PMID 34207556, 2021). "We also detected a significant positive correlation between the expression levels of CHRNA5 and CHEK1 in CCLE, TCGA and METABRIC breast cancer datasets." (PMID 30543688, 2018).
breast carcinoma (continued). "The observed positive correlations between CHRNA5 and CHEK1 mRNA expression levels in CCLE, TCGA and METABRIC breast cancer datasets are supportive of CHRNA5 RNAi findings in MCF7." (PMID 30543688, 2018). "However, there is no study examining the association of CHRNA5 with CHEK1 or DDR in breast cancer." (PMID 30543688, 2018). "The development of breast carcinoma subtypes-in-mouse PDX models has helped the identification of small chemical inhibitors to PI3K, checkpoint kinase 1, aurora kinase, BCL-2 family-BH3 mimetic, and many other drugs approved for treatment of breast cancers." (PMID 27746730, 2016). "The close cross-talk between CHEK1 and BRCA1, the breast cancer tumour suppressor gene, at the G2/M checkpoint suggests the potential importance of this pathway in breast cancer." (PMID 23844225, 2013). "As a result, CHEK1 and HOTAIR also served as oncogenic roles in breast cancer." (PMID 38561760, 2024). "Interestingly, expressions of CHEK1 and UBE2C were positively correlated with each other in luminal A breast cancer subtype, suggesting the existence of a potential co-regulatory network for both genes." (PMID 35903365, 2022). "Nonetheless, our results showed that RNF126-depleted breast cancer cells were not sensitive to CHEK1 and ATR inhibitors." (PMID 36539893, 2022). "LncRNA LINC02582 could promote breast cancer radioresistance by interacting with deubiquitinating enzyme ubiquitin specific peptidase 7 (USP7) to deubiquitinate and stabilize checkpoint kinase 1 (CHK1), a key molecule in DDR12." (PMID 36323697, 2022). "Importantly, CHEK1 and PLK1 were found to be poor prognostic biomarkers for the survival of breast cancer patients, further supporting that enhanced DNA damage repair mechanisms in cancer cells play a catastaltic role in efficient radiotherapy." (PMID 33898418, 2021). "Although an inhibitor of checkpoint kinase 1 (Chk1) suppresses the growth and motility of breast cancer cell lines, no study has investigated the effects of the combined use of a Chk1 inhibitor and radiation on cancer metastasis." (PMID 34124754, 2021). "Evidence indicated CHEK1 may implicate with multiple cancers, including NSCLC, breast cancer, and ovarian cancer." (PMID 33287830, 2020). "EVs from irradiated breast cancer cells were taken up by human primary mammary epithelial cells, inducing an increased phosphorylation of ATM, Histone H2AX, and checkpoint kinase 1 (Chk1) in recipient cells indicating the induction of DNA damage repair responses." (PMID 31698689, 2019). "These genes include AURKB, BUB1, CHEK1, FOXM1, KIFC1, and TTK7, five of which, BUB1, CHEK1, FOXM1, KIFC1, and TTK, we have also identified and have functionally validated to have a selective requirement for cell growth in breast cancer cell models." (PMID 29535384, 2018). "High expression of RNF126 is an independent predictor of a poor prognosis in invasive breast cancer and is considered a potential biomarker for cancer responsiveness to checkpoint kinase 1 (CHK1) inhibitors, as RNF126 increases gene expression of CHK1 in breast cancer cells." (PMID 30529286, 2018). "The most significant associations for breast cancer risk in SBCS came from rs6805118 in ATR (p=7.6x10-5) and rs2155388 in CHEK1 (p=3.1x10-6), but neither remained significant after meta-analysis with other studies." (PMID 23844225, 2013). "Because of this opposite clinical significance and the predicted miRNA‐mRNA interactions, we used transfection of hsa‐miR‐195‐5p miRNA mimics to one ER‐ and two ER+ breast cancer cell lines and identified hsa‐miR‐195‐5p as a negative regulator of CHEK1 independently of ER expression." (PMID 40548926, 2025).
breast carcinoma (continued). "However, in contrast to gemcitabine-treated DLBCL cells, there was no shift for proteins in the ssDNA binding RPA complex or CHEK1 in cisplatin-treated breast cancer cells." (PMID 40335468, 2025). "This analysis sought to confirm the specific upregulation of CHEK1 and PLK1 in TNBC, as suggested by the initial microarray findings and cross-platform verification analysis, and to contextualize their expression within the broader landscape of breast cancer subtypes." (PMID 39473450, 2024). "This could involve techniques such as quantitative PCR, Western blotting, or immunohistochemistry to confirm the overexpression of CHEK1 and PLK1 at both mRNA and protein levels in TNBC tissues compared to normal breast tissues and other breast cancer subtypes." (PMID 39473450, 2024). "Among those, CHEK1 is a checkpoint kinase that is essential for normal and cancer cells, GATA3 is a critical transcription factor with known oncogenic role, and RAD51 has been reported as an oncogene with elevated expression in multiple cancer types including breast cancer." (PMID 31980032, 2020). "We could detect high levels of both CHEK1 splice isoforms in RNA purified from a small panel of breast cancer tissues, although we did not see an enrichment of either isoform in any particular tumour type at the RNA level." (PMID 25208576, 2014). "Notably, we were not only able to confirm CHEK1 aberration (with over-expression) in basal-like tumors (which are enriched for TNBC), but also reveal this aberration in the luminal B subtype, suggesting a possible vulnerability of this more aggressive type of breast cancer." (PMID 34115745, 2021). "However, we conclude that the response is likely not CHEK1 dependent, when ADDR response for cisplatin in MDA-MB-231 breast cancer cells does not coincide with CHEK1 activation." (PMID 40335468, 2025). "Interestingly, although we have previously reported that RNF126 knockdown reduces CHEK1 expression, we did not observe a synergistic lethal effect of ATR inhibitors on breast cancer cells with knockdown of RNF126." (PMID 36539893, 2022). "Kinases BUB1, CHEK1, IRAK1, TTK, RYK, and VRK2, identified in this study, for example, have been reported to be highly overexpressed in ER-negative breast tumors and were critical for the growth of either ER-negative only or both ER-positive and -negative breast cancer cells." (PMID 22309939, 2012).
ovarian carcinoma (116 papers, 2007 to 2026). A malignant neoplasm originating from the surface ovarian epithelium. "In OC cells, RAD1 and CHEK1 knockdown led to decreased cellular viability, increased sensitivity to cisplatin, and decreased HRR efficiency, while CHEK1 overexpression was associated with detrimental outcomes in early-stage ovarian cancer." (PMID 32512900, 2020). "In one of these screens, CHEK1 loss sensitized ovarian cancer cells to IKKε loss." (PMID 27558154, 2016). "Similar action was also found in ovarian cancer stem cells that EZH2 transcriptionally up-regulates checkpoint kinase 1 expression by directly binding to its promoter, therefore promoting ovarian cancer chemoresistance." (PMID 40028035, 2025). "Conversely, studies involving ovarian cancer patients have shown that combining CHEK1 inhibitors with standard chemotherapy improved progression-free survival, suggesting potential for therapeutic synergy." (PMID 39473450, 2024). "Using a panel of ovarian cancer cell lines, we show a significant correlation between increased nuclear phosphorylated checkpoint kinase 1 (pCHK1) staining and increased sensitivity to elimusertib." (PMID 36373784, 2023). "In a recent report, inhibition of ataxia telangiectasia and Rad3-related checkpoint kinase 1 (ATR-Chk1) was shown to enhance oncolytic toxicity of adenovirus in ovarian cancer by using the small molecule inhibitor UCN-0134." (PMID 35948546, 2022). "HOTAIR facilitated paclitaxel resistance by regulation of checkpoint kinase 1 (CHEK1) in ovarian cancer." (PMID 36105363, 2022). "It was developed by Eli Lilly to cure ovarian cancer patients by targeting CHEK1, a serine/threonine-specific protein kinase." (PMID 35742913, 2022). "Ovarian cancer cells often carry BRCA1 or BRCA2 (BRCA1/2), germline or somatic mutations in ataxia telangiectasia and Rad3-related protein (ATR) or checkpoint kinase 1 (CHK1) genes of the homologous recombination (HR) pathway." (PMID 34072593, 2021). "For instance, DDRis, namely PARP inhibitors (PARPi) and checkpoint kinase 1 (CHK1) inhibitor, have predominantly been studied in patients with breast or ovarian cancers." (PMID 34930377, 2021). "Many other genes in the cell cycle pathway, such as CDC7, CDK1 and CHEK1, have previously been reported to be correlated with the proliferation and chemoresistance of ovarian cancer." (PMID 34876569, 2021). "CHEK1 acts as an oncogene in various cancers, including pancreatic cancer, non-small cell lung cancer, and ovarian cancer." (PMID 32766141, 2020). "The poor prognosis in ovarian cancer patients with higher CHEK1 expression was in line with the data from the Kaplan–Meier plotter analysis." (PMID 32178478, 2020). "Inhibitors against proteins coded by these genes, such as AURKA and B or CHEK1, are currently in clinical development, so our findings provide support for the specific development of those agents in ovarian cancer." (PMID 29575713, 2018). "We proceeded to evaluate the combined efficacy of CHEK1 inhibitor with topotecan, a salvage treatment for platinum-resistant ovarian cancer, showing a synergistic cytotoxic effect with reduced dosages of both drugs." (PMID 27558154, 2016). "This approach potentially widens the therapeutic index by preferentially targeting the ovarian cancer-specific dependence on upregulated or activated CHEK1, and allowing increased cancer cell killing at lower doses of each drug." (PMID 25884494, 2015). "Decreased levels of CHEK1 S296 autophosphorylation have been correlated with response to CHEK1 inhibition in colon, breast, and ovarian cancer cell lines." (PMID 25884494, 2015). "Our findings suggest that the addition of CHEK1 inhibitor increases the response of ovarian cancer cells to TPT." (PMID 25884494, 2015).
ovarian carcinoma (continued). "We recently found that CHEK1 gene was overexpressed in most of HGS ovarian cancer, and combined inhibition of pro-survival modulator, IKKε, cooperatively induced apoptosis in ovarian cancers." (PMID 25884494, 2015). "In our study, we found that high expression of CHEK1 was associated with poor prognosis of NSCLC; similar associations were observed in ovarian cancer." (PMID 25840419, 2015). "Our study shows that TPT synergistically induces cytotoxicity in combination with CHEK1 inhibitor especially in HGS ovarian cancer cells." (PMID 25884494, 2015). "As shown in this study, this marker is expressed in HGS ovarian cancer cell lines at steady states and CHEK1 gene is over-expressed in nearly all cases of TCGA HGS ovarian cancers." (PMID 25884494, 2015). "A recent study on ovarian cancer supports our observation that the cell cycle proteins, CHEK1 and BUB1, are over-expressed and are important to the tumor condition, lending support to our observation." (PMID 23383610, 2013). "Recently, high-throughput RNAi screen identified CHEK1 as target for sensitizing ovarian cancer cells to cisplatin and pancreatic cancer cells to gemcitabine as well as mesothelioma cells to doxorubicin." (PMID 22905093, 2012). "As specified in the introduction, CHEK1 overexpression was frequently observed in solid tumors, indicating its role in the prognosis of melanoma, lung adenocarcinoma, hepatocellular carcinoma, bladder cancer, brain cancer, ovarian cancer, and BrC." (PMID 40344565, 2025). "In this study, using gene expression profiling of 24 cell lines from different cancer types and in a panel of ovarian cancer cell lines, we found that nuclear‐specific enrichment of checkpoint kinase 1 (CHK1) correlated with increased sensitivity to elimusertib." (PMID 36373784, 2023). "Overexpression of CHEK1 weakened HOTAIR knockdown-induced paclitaxel sensitivity in ovarian cancer." (PMID 36105363, 2022). "Indeed, a promising synergistic antitumoral effect between AURKA and CHEK1 inhibitors in ovarian cancer has been described." (PMID 32512900, 2020). "We previously found that CHEK1 was overexpressed in most HGS ovarian cancers, and hypothesized that inhibition of CHEK1 would increase the therapeutic index of TPT, given its importance in DNA damage repair pathways." (PMID 25884494, 2015). "We hypothesized that the combination of olaparib with anticancer agents that disrupt HRR by targeting ataxia telangiectasia and Rad3-related protein (ATR) or checkpoint kinase 1 (CHK1) may be an effective strategy to reverse ovarian cancer resistance to olaparib." (PMID 33352723, 2020). "The Phase I/II trial investigated the novel checkpoint kinase 1 (Chk1) inhibitor SRA737 in combination with gemcitabine, demonstrating tumor responses in patients with ovarian cancer." (PMID 39337506, 2024). "Many clinical trials, including trials evaluating drugs targeting ATR, ATM, WEE1, checkpoint kinase 1/2 (CHK1/2), BRCA1/2 and RAD51, have been designed to evaluate interference with DDR pathways to overcome platinum and PARPi resistance in ovarian cancer." (PMID 38539161, 2024). "Prexasertib, a promising CHEK1 and CHEK2 inhibitor tested in ovarian cancer patients would be a candidate for treating CLL." (PMID 35301276, 2022). "High expression of GJB2, S100A2, SPOCK2, TGM1or EPS8 indicated a poor OS of patients with ovarian cancer, whereas ovarian cancer patients with higher expression of ADAMDEC1, CHEK1, EGFL6, FAM181A, FOXA2, LYPD1, PART1 or XPR1 possessed better OS." (PMID 31794425, 2019). "When combined with CHEK1 inhibitor, TPT potently and synergistically inhibited the proliferation of HGS ovarian cancer cells." (PMID 25884494, 2015). "Thus, combination therapy of CHEK1 inhibitor with DNA damaging agents such as TPT could introduce an analogous strategy for targeting non-BRCA mutated or BRCA-like HGS ovarian cancers." (PMID 25884494, 2015).
ovarian carcinoma (continued). "CHEK1 activation upon TPT treatment may potentially provide the resistance and relapse to TPT monotherapy especially in CHEK1-overexpressing HGS ovarian cancer patients." (PMID 25884494, 2015). "Most HGS ovarian cancers, however, do not have BRCA mutations, but do have elevated expression of CHEK1." (PMID 25884494, 2015). "Here, we report that the overexpressed genes IRAK1, CHEK1 and BUB1 may play an important role in ovarian cancer." (PMID 23383610, 2013). "This study suggests that of the 17 shortlisted genes flagged as significant, the overexpressed genes IRAK1, CHEK1 and BUB1 may play an important role in ovarian cancer." (PMID 23383610, 2013). "Many reports indicate that ATR-CHK1 activation may promote tumor growth and that CHEK1 expression is upregulated in triple-negative breast cancer, neuroblastoma, T-cell leukemia, nasopharyngeal cancer, ovarian cancer, and glioblastoma." (PMID 32610557, 2020). "Therefore, we investigated whether CHEK1 inhibitor, PF477736, sensitized HGS ovarian cancer cell lines to TPT treatment." (PMID 25884494, 2015). "Here, we found that HGS ovarian cancer cell lines generally required higher concentrations of TPT, in the absence of CHEK1 inhibition, to achieve equivalent cytotoxicity compared to non-HGS ovarian cancer cell lines." (PMID 25884494, 2015).